FAM86HP (family with sequence similarity 86 member H, pseudogene)
Gene: Transcribed unprocessed pseudogene on chromosome 3 (130,099,258 to 130,111,472, reverse strand). Ensembl gene ENSG00000253540.
Diseases named in the same sentence as FAM86HP in open-access papers:
FAM86HP is named in the same sentence as 2 diseases in open-access papers, as found by Europe PMC text mining. Sharing a sentence is not in itself a finding about the gene and the disease. The quoted sentences say what the papers report.
proctitis (1 paper, 2020). An inflammatory process affecting the anus. "The ALG1L2 mapped to the significant CNV region on chr3:129690192–129,896,364 (along with TRH and FAM86HP) was also found to be associated with proctitis in the transcriptomic analysis of whole-blood tissue, while the other two genes (TRH & FAM86HP) were not predicted in either of the two tissues." (PMID 33008348, 2020).
rubella (1 paper, 2023). A viral infection caused by the rubella virus. "In rubella, including five in whole blood (JAGN1, RRP12, RP11-452K12.7, CASP7, and AP3S2), four in the lung tissue (IL17RC, FAM86HP, AMACR, and RRP12), and four in the transformed fibroblast cells (PPP2R1B, C11orf1, DLAT, and TMEM117)." (PMID 37020999, 2023).